ENSG00000282936 (novel protein)
Synonyms: LOC122526780
Gene: Protein-coding gene on chromosome 17 (6,578,147 to 6,640,711, reverse strand). Ensembl gene ENSG00000282936.
Homologues: Orthologues: mouse 4933427D14Rik (44% identical).